HCCS (holocytochrome c synthase)
Description:
Lyase that catalyzes the covalent linking of the heme group to the cytochrome C apoprotein to produce the mature functional cytochrome.
Synonyms: CCHL; LSDMCA1; MCOPS7; MLS
Tractability: PROTAC: ubiquitination databases record sites on it; its protein half-life has been measured.
Target class: Enzyme; Lyase
Gene: Protein-coding gene on chromosome X (11,111,299 to 11,123,086, forward strand). Ensembl gene ENSG00000004961.
Subcellular location: Mitochondrion inner membrane; Membrane
Subcellular location (Human Protein Atlas): Mitochondria; Cytosol
Pathways (Reactome):
Metabolism: Respiratory electron transport
Gene Ontology:
Molecular function: heme binding; holocytochrome-c synthase activity; protein binding
Biological process: cytochrome c biosynthetic process; cytochrome c-heme linkage; animal organ morphogenesis; respiratory electron transport chain
Cellular component: membrane; mitochondrion; mitochondrial inner membrane; cytosol
Homologues: Orthologues: chimpanzee HCCS (100% identical), macaque HCCS (99% identical), dog HCCS (93% identical), rat Hccs (88% identical), pig HCCS (87% identical), mouse Hccs (85% identical), rabbit HCCS (84% identical), tropical clawed frog hccs (71% identical), zebrafish hccsb (67% identical), zebrafish hccsa.1 (64% identical), Drosophila melanogaster Cchl (54% identical), Caenorhabditis elegans cchl-1 (49% identical), and 1 more.
Diseases named in the same sentence as HCCS in open-access papers:
HCCS is named in the same sentence as 40 diseases in open-access papers, as found by Europe PMC text mining. Sharing a sentence is not in itself a finding about the gene and the disease. The quoted sentences say what the papers report.
microphthalmia (13 papers, 2013 to 2024). Congenital or developmental anomaly in which the eyeballs are abnormally small. "HCCS mutation has been shown to be associated with the microphthalmia with linear skin defects or MIDAS (microphthalmia, dermal aplasia, and sclerocornea) syndrome, an X-linked disorder with male lethality." (PMID 32370309, 2020). "Previously identified mitochondrial proteins associated with the development of microphthalmia, namely HCCS and COX7B, were shown to induce a reactive oxygen species (ROS)‐dependent induction of caspase 9‐mediated cell death." (PMID 30389680, 2019). "Here we report the first familial cases in which unilateral microphthalmia with linear skin defects in the mother and isolated microphthalmia in the daughter are caused by a microdeletion spanning the entire HCCS gene and part of ARHGAP6." (PMID 23401659, 2013). "In addition, it has been found that HCCS also has an important role in apoptosis and that the HCCS variant is associated with microphthalmia with linear skin defects syndrome, which is an X-linked male-lethal disorder." (PMID 34728707, 2021). "Interestingly, HCCS was the first human gene encoding for an MRC protein which causes microphthalmia when mutated." (PMID 33670341, 2021). "There is also wider significance to our observations: HCCS mutation in humans causes microphthalmia with linear skin lesions (MLS), but insight into HCCS catalysis, and thus the mechanistic consequence(s) of HCCS mutation, are in their infancy (13, 24, –, 26)." (PMID 33947751, 2021). "In our case, we describe a newborn with mosaic deletion encompassing HCCS gene resulting in unilateral microphthalmia and facial skin lesions." (PMID 30068298, 2018). "The disease, microphthalmia with linear skin defects (MLS), is due to mutations in the HCCS gene." (PMID 33291601, 2020). "Microphthalmia with linear skin defects syndrome (MLS), or linear skin defects with multiple congenital anomalies 1 (LSDMCA1), also features linear skin defects and hearing impairment, and is caused by pathogenic variants in the holocytochrome c-type synthase-encoding HCCS gene." (PMID 33396879, 2020). "In conclusion, we report on a family with two cases of unilateral microphthalmia of whom only one showed scars of neonatal linear skin lesions with a 185–220 kb microdeletion containing HCCS and ARHGAP6, supporting the hypothesis that HCCS is a candidate gene for severe eye malformations." (PMID 23401659, 2013).
breast carcinoma (4 papers, 2020 to 2026). "We further evaluated the prognostic relevance of HCCS expression across breast cancer and its subtypes using independent datasets and found that elevated HCCS mRNA levels were consistently associated with poor prognosis." (PMID 41476662, 2025). "In summary, these findings highlight a possible association between HCCS expression and the immune landscape of breast cancer, but additional experimental validation is necessary to confirm mechanistic involvement." (PMID 41476662, 2025). "Further analysis revealed a significant association between HCCS methylation and clinical parameters such as cancer stage, menopause status, patient age, and breast cancer subtypes." (PMID 41476662, 2025). "Validation across independent datasets consistently supported the association of elevated HCCS expression with poor prognosis in breast cancer." (PMID 41476662, 2025). "Collectively, these findings highlight that higher HCCS mRNA expression is consistently associated with poor prognosis in breast cancer, in agreement with our earlier analyses." (PMID 41476662, 2025). "Given that IDC is the most prevalent and often more aggressive histological form, this observation supports the hypothesis that HCCS overexpression may be associated with more invasive breast cancer phenotypes." (PMID 41476662, 2025). "Following our pan‐cancer findings, we focused our analysis on breast cancer to explore the clinical significance of HCCS expression in greater detail." (PMID 41476662, 2025). "Our analysis revealed a robust association between elevated HCCS expression and reduced RFS, with the strongest effects observed in aggressive breast cancer subtypes." (PMID 41476662, 2025). "Overall, our findings indicate that HCCS is not only overexpressed in breast cancer but its expression correlates with aggressive clinical and molecular features, particularly in TNBC." (PMID 41476662, 2025). "HCCS was significantly overexpressed in multiple cancers, with the highest upregulation observed in breast cancer, particularly TNBC." (PMID 41476662, 2025). "Although HCCS has been studied in mitochondrial disorders, its role in cancer—particularly breast cancer—remains largely unexplored." (PMID 41476662, 2025). "This integrated bioinformatics analysis highlights HCCS as a potential prognostic biomarker and therapeutic target in breast cancer, particularly in TNBC, although further experimental validation is required before clinical application." (PMID 41476662, 2025). "Given the upregulation of HCCS in multiple cancers, particularly in breast cancer and TNBC, constructing these gene interaction networks enhances our understanding of its role in oncogenesis." (PMID 41476662, 2025). "Notably, patients with lower HCCS expression exhibited a marginally better OS outcome than those with higher expression, suggesting that lower HCCS expression may be associated with a favorable prognosis in breast cancer." (PMID 41476662, 2025). "Patients with elevated HCCS expression exhibited significantly poorer OS across all breast cancer subtypes (p = 0.038)." (PMID 41476662, 2025). "Our GSEA results establish HCCS and its network as central to a critical metabolic axis in breast cancer, governing heme biosynthesis, cytochrome c maturation, and mitochondrial bioenergetics." (PMID 41476662, 2025). "We previously reported that a 4-gene score derived from the tumor expression of DOK4, HCCS, PGF, and SHCBP1 genes is associated with tumor aggressiveness and can be considered as a potential predictive biomarker for breast cancer." (PMID 32650578, 2020).
breast carcinoma (continued). "Our study provides compelling evidence that HCCS is a critical player in breast cancer progression and may serve as a novel biomarker and therapeutic target." (PMID 41476662, 2025). "Collectively, these findings suggest that HCCS may serve as a significant prognostic biomarker in breast cancer, with distinct implications for relapse‐free and distant metastasis‐free survival." (PMID 41476662, 2025). "To determine whether HCCS dysregulation was unique to breast cancer or part of a broader oncogenic pattern, we extended our analysis to other tumor types not previously highlighted in TCGA pan‐cancer analysis." (PMID 41476662, 2025). "We further analyzed HCCS expression across histological subtypes of breast cancer." (PMID 41476662, 2025). "Finally, the study did not explore the underlying molecular mechanisms linking HCCS expression to breast cancer progression, highlighting the need for further functional studies to elucidate the biological pathways involved." (PMID 41476662, 2025). "In breast cancer cell lines (MDA-MB-231), the effects of HCCS knockdown on cell proliferation and cell cycle distribution were assessed using CCK-8, colony formation, and flow cytometry assays." (PMID 42232519, 2026). "Notably, postmenopausal patients with high HCCS expression exhibited significantly worse survival outcomes compared to premenopausal patients (p < 0.0001), suggesting a possible role of HCCS in modulating disease progression in postmenopausal breast cancer patients." (PMID 41476662, 2025). "In particular, we did not perform siRNA‐mediated knockdown of HCCS in breast cancer cell lines to evaluate the resulting phenotypic effects." (PMID 41476662, 2025). "HCCS is significantly overexpressed in various cancers, particularly in breast cancer and triple‐negative breast cancer (TNBC)." (PMID 41476662, 2025). "As we previously reported, the four-gene score has reflected cell proliferation in breast cancer by measuring gene expressions of DOK4, HCCS, SHCBP1, and PGF; it was of interest to investigate the distribution of the score in other types of cancer in The Cancer Genome Atlas (TCGA) project." (PMID 33291601, 2020). "The mechanistic pathways underlying the observed prognostic effects of HCCS expression in aggressive subtypes such as TNBC was not explored, warranting further in vitro and in vivo studies to elucidate the biological role of HCCS in breast cancer progression." (PMID 41476662, 2025). "Furthermore, DMFS analysis revealed that patients with low HCCS expression demonstrated significantly higher DMFS compared to those with elevated expression (n = 2765, HR = 1.28 [1.09–1.49], p = 0.002), further supporting the prognostic relevance of HCCS in breast cancer progression." (PMID 41476662, 2025).
autism (1 paper, 2014). Persistent deficits in social interaction and communication and interaction as well as a markedly restricted repertoire of activity and interest as well as repetitive patterns of behavior. "The deletion encompasses both the HCCS gene and several autism X-linked genes, suggesting that large Xp deletions might be associated with both MLS and ASD, probably due to the deletion of contiguous genes." (PMID 25182979, 2014).
breast invasive carcinoma (1 paper, 2025). "HCCS was found to be significantly upregulated in multiple cancer types, including breast invasive carcinoma (BRCA), kidney chromophobe (KICH), lung adenocarcinoma (LUAD), lung squamous cell carcinoma (LUSC), and uterine corpus endometrial carcinoma (UCEC)." (PMID 41476662, 2025).
breast tumor (1 paper, 2025). "Using TCGA‐BRCA transcriptomic data accessed via UALCAN, we confirmed that HCCS expression is significantly upregulated in breast tumor tissues compared to normal breast tissues." (PMID 41476662, 2025). "HCCS was found to be markedly upregulated in breast tumors, where its expression correlated with key clinicopathological features including nodal metastasis, stage, and patient prognosis." (PMID 41476662, 2025). "Consistent with our discovery cohort, HCCS was significantly upregulated in breast tumors compared with normal tissues (p = 5.192E − 07, Student’s t test)." (PMID 41476662, 2025). "This differential expression suggests a potential oncogenic role for HCCS in breast tumor biology." (PMID 41476662, 2025).
cancers of the adrenal gland (1 paper, 2025). "This analysis confirmed elevated HCCS expression in various malignancies, notably in cancers of the adrenal gland, bladder, breast, esophagus, liver, lung, ovary, pancreas, prostate, rectum, kidney, skin, stomach, testis, thyroid, and uterus." (PMID 41476662, 2025).
cardiomyopathy (1 paper, 2017). A disease of the heart muscle or myocardium proper. "We suggest that individuals with MLS syndrome or variants or cytogenetic abnormalities involving NDUFB11, HCCS, or COX7B should be considered at risk for histiocytoid CM and screening for evidence of malignant arrhythmias and cardiomyopathy may be appropriate." (PMID 28050600, 2017).
cervical squamous cell carcinoma (1 paper, 2025). A squamous cell carcinoma arising from the cervical epithelium. "Using TNMplot, we analyzed the expression of HCCS in several cancers, including cervical squamous cell carcinoma (CESC), head and neck squamous cell carcinoma (HNSC), thyroid carcinoma (THCA), and pheochromocytoma and paraganglioma (PCPG)." (PMID 41476662, 2025).
enamel hypoplasia (1 paper, 2024). "In addition, a duplication of uncertain significance including both HCCS and AMELX was identified in a male with corneal anomalies, glaucoma, an atrial septal defect, and enamel hypoplasia along with a family history of developmental ocular disorders consistent with X-linked inheritance." (PMID 39766903, 2024).
Gillespie syndrome (1 paper, 2016). "We were also unable to find mutations in the neighbouring gene, HCCS, in the other Gillespie syndrome cases in our cohort." (PMID 27124303, 2016).
invasive ductal carcinoma (1 paper, 2025). "HCCS levels were notably elevated in invasive ductal carcinoma (IDC) and medullary carcinoma compared to invasive lobular carcinoma (ILC) and other less common subtypes." (PMID 41476662, 2025).
Miller-Dieker syndrome (1 paper, 2017). "These included well characterised syndrome regions eg Di-George (OMIM 188400), Williams (OMIM 194050) and Miller-Dieker syndrome (OMIM 247200) regions as well as smaller imbalances with imbalance of critical genes eg PAFAH1B1 (OMIM 601545) and HCCS (OMIM 300056) genes." (PMID 28396697, 2017).
neurocutaneous disorder (1 paper, 2014). "Somatic mosaicism could be one factor contributing to a variable phenotype, however, cell selection mechanisms including OXPHOS defect and/or enhanced cell death upon HCCS deficiency likely underlie the great clinical variability in this rare neurocutaneous disorder." (PMID 24735900, 2014).
pancreatic cancer (1 paper, 2018). "In pancreatic cancer, the transition between IOIPMN to IPMC includes the following genes: FAR1, CEACAM1, HCCS." (PMID 33265245, 2018).
sclerocornea (1 paper, 2014). A corneal disease in which the cornea blends with sclera, resulting in clouding of the cornea. "Segmental Xp22.2 monosomy or a heterozygous HCCS mutation is associated with the microphthalmia with linear skin defects (MLS) or MIDAS (microphthalmia, dermal aplasia, and sclerocornea) syndrome, an X-linked disorder with male lethality." (PMID 24735900, 2014).
cancer (6 papers, 2016 to 2026). A tumor composed of atypical neoplastic, often pleomorphic cells that invade other tissues. "Given the significant relationship between HCCS expression, its methylation status, and cancer progression, these mutational alterations further highlight HCCS’s potential role in tumorigenesis." (PMID 41476662, 2025). "To further investigate the genetic alterations of HCCS that may contribute to its dysregulation in cancer, we explored its mutational landscape using data from the Catalogue of Somatic Mutations in Cancer (COSMIC) database." (PMID 41476662, 2025). "To evaluate whether HCCS expression is associated with key clinical variables, we performed a subgroup meta‐analysis stratified by clinical features, including nodal metastasis status, individual cancer stages, gender, race, menopausal status, and age." (PMID 41476662, 2025). "To further explore the molecular role of HCCS in cancer, we examined its gene and protein interaction networks, aiming to elucidate its broader biological functions and the regulatory pathways it influences." (PMID 41476662, 2025). "Together, these analyses of gene and protein interactions underscore the importance of HCCS in cancer biology, especially in aggressive cancer subtypes like TNBC." (PMID 41476662, 2025). "Merging evidence, however, indicates that HCCS also influences inflammatory responses, redox balance, and immune regulation, expanding its role in cancer biology beyond energy metabolism." (PMID 41476662, 2025). "To assess the dysregulation of HCCS in cancer, we employed RNA‐sequencing datasets from TCGA using the TIMER2.0 platform, which compares gene expression between tumor and matched normal tissues." (PMID 41476662, 2025). "Dysregulation of HCCS can impair mitochondrial respiration and apoptotic signaling, enabling cancer cells to evade cell death." (PMID 41476662, 2025). "Pan-cancer analysis suggested that HCCS might act as a mitochondrial-immunometabolic hub involved in immune evasion." (PMID 42232519, 2026). "Given the importance of mitochondrial dynamics in tumor biology, HCCS dysregulation could influence cancer cell survival, metabolic reprogramming, and resistance to therapy." (PMID 41476662, 2025). "This suggests HCCS may serve as a molecular link between mitochondrial dysfunction, apoptosis resistance, and cancer pathobiology." (PMID 41476662, 2025). "Holocytochrome c synthase (HCCS), a mitochondrial enzyme essential for cytochrome c maturation, may play a pivotal role in cancer pathogenesis." (PMID 41476662, 2025). "These interactors are likely involved in critical cellular processes and may offer insight into the functional role of HCCS in cancer." (PMID 41476662, 2025). "Blocking the route of copper to SOD1 through hCCS has been shown to inhibit cancer proliferation." (PMID 27282955, 2016). "The PPI network analysis further revealed key interactors such as COX10 and FECH, which are involved in mitochondrial function and heme metabolism, supporting the idea that HCCS could influence mitochondrial dynamics and cellular energy production in cancer cells." (PMID 41476662, 2025). "In cancer, particularly TNBC—a subtype characterized by metabolic rewiring and defective apoptosis—aberrant expression of mitochondrial regulators such as HCCS may create a permissive environment for tumor progression and therapy resistance." (PMID 41476662, 2025).